RET (ret proto-oncogene)
Diseases named in the same sentence as RET in open-access papers (continued):
Sharing a sentence is not in itself a finding about the gene and the disease.
thyroid cancer (continued). "For rare NTRK and RET fusion-positive metastatic, RAI-resistant thyroid cancers, variable success of re-induction of RAI avidity during treatment with NTRK or RET inhibitors has been reported." (PMID 38642578, 2024). "Promising early efficacy data in LIBRETTO-001 alongside the efficacy data demonstrated in the 343 patients with RET fusion-positive NSCLC and thyroid cancer enrolled in the same trial allowed the drug to gain the accelerated FDA approval designation." (PMID 39518080, 2024). "The FDA approval was supported by 343 patients with RET gene fusion-positive NSCLC and thyroid cancer in the same trial." (PMID 39061168, 2024). "ALK fusions were predominantly observed in lung cancer and lymphoma, while RET, ABL1, and BRAF fusions have been identified most frequently in thyroid cancer, leukemias, and pediatric low-grade gliomas, respectively." (PMID 38877018, 2024). "In phase II, the clinical efficacy of pralsetinib was evaluated in nine cohorts in various tumors with RET activity, mainly NSCLC and thyroid cancer." (PMID 37651020, 2024). "Common genetic alterations found in thyroid cancer include BRAF V600E, NRAS, HRAS, KRAS, RET/PTC, and TERTp." (PMID 39456540, 2024). "During the last decade there has been an evolution in the treatment of resistant/refractory thyroid cancer, by inducing targeted therapies (anti-VEGF, anti-RET, anti-PDGF etc.), the so-called Multiple Kinase Inhibitors (MKI’s)." (PMID 39458070, 2024). "Multikinase inhibitors, such as sorafenib and lenvatinib, have been used successfully to treat thyroid carcinoma, and specific inhibitors for genetic abnormalities acquired early, such as BRAF, RET, and NTRK alterations, are effective." (PMID 38630010, 2024). "However, BRAF mutations and RET and NTRK fusions, major markers for molecularly targeted therapies in thyroid carcinoma, are considered early molecular events in thyroid carcinogenesis, which may indicate their presence in lymph node metastases similar to their primary lesions." (PMID 39560912, 2024). "In this article, we review the current status on the use of the selective RET inhibitor, selpercatinib, in RET fusion-positive tumors: NSCLC, thyroid cancers, and the more recent tissue-agnostic activity leading to FDA approval." (PMID 37360768, 2023). "Oncogenic RET fusions are present in nearly 2% of patients with non-small cell lung cancer (NSCLC), 10–20% of patients with thyroid cancer, and <1% across the pan-cancer spectrum." (PMID 37360768, 2023). "In addition to selective RET inhibition for the treatment of patients with RET alterations, inhibitors of NTRK fusions (tropomyosin receptor kinase [TRK] inhibitors) and BRAF mutations (BRAF inhibitors) have either been approved or have shown promising activity in thyroid cancer." (PMID 37207147, 2023). "Selpercatinib has led to a paradigm change in the management of RET fusion-positive solid tumors including NSCLC and thyroid cancer." (PMID 37360768, 2023). "Selpercatinib and pralsetinib have received regulatory approvals in RET-altered non-small cell lung cancer (NSCLC) and thyroid cancer." (PMID 38118420, 2023). "The treatment landscape for thyroid cancers has changed rapidly with the availability of kinase inhibitors against VEGFR, BRAF, MEK, NTRK, and RET." (PMID 37434642, 2023). "With the development and marketing of selective RET inhibitors, selpercatinib and pralsetinib were successively approved by the FDA for the treatment of RET fusion-positive advanced NSCLC and thyroid cancer." (PMID 37924363, 2023). "We utilized pentaplex panel testing for 23 lung carcinomas, 23 sarcomas, 4 thyroid carcinomas, 3 salivary gland tumors, and 3 pancreatic carcinomas with oncogenic gene translocations (ALK: 31; ROS1 10; RET: 9; NTRK1: 2; NTRK3: 4)." (PMID 37686416, 2023). "An important research result in thyroid cancer, inhibition of FGF receptor blocks adaptive resistance to RET inhibition in CCDC6-RET-rearranged thyroid cancer." (PMID 36582799, 2022).
thyroid cancer (continued). "Evaluation of thyroid FNAs with the Unified Assay identified all fusion proteins described for thyroid cancer in TCGA, the most common fusion pair being PAX8-PPARg, with other common fusion partners including RET, NTRK1/3, ALK, and BRAF." (PMID 36675685, 2022). "Of the 77 patients with thyroid cancers, six (7.8%) RTK fusion events were identified, which were exclusively RET fusions." (PMID 36369474, 2022). "To date, two highly potent RET-specific TKIs, selpercatinib and pralsetinib, have been approved by the US Food and Drug Administration (FDA) for the treatment of advanced or metastatic RET-altered NSCLC and thyroid cancers." (PMID 36059009, 2022). "Of these, 29 patients had RET fusion–positive solid tumors, excluding RET fusion–positive NSCLC or thyroid cancer, and were included in the safety population presented here." (PMID 35962206, 2022). "Lastly, a PDAC case was found to have an RET fusion, for which RET kinase inhibitors such as selpercatinib and pralsetinib are currently approved in NSCLC and thyroid cancer." (PMID 35849877, 2022). "The stable transgenic fly lines were generated by standard methods to create GMRd-RET, GMR-dRETC695R, and GMR-dRETM1007TDrosophila thyroid cancer models." (PMID 36003330, 2022). "Selpercatinib and pralsetinib are the only selective RET inhibitors FDA-approved for treatment of RET fusion-positive lung and thyroid cancers and show potent intracranial activity." (PMID 35957881, 2022). "RET gene alterations are also found in a small proportion of patients with NSCLC, but additionally, can be present in certain histological types of thyroid cancer (medullary and papillary)." (PMID 35055414, 2022). "Molecular testing has been increasingly utilized to assist with indeterminates as approximately seventy percent of differentiated thyroid cancers have detectable abnormalities involving BRAF, RAS, RET/PTC, or PAX8/PPAR gamma." (PMID 33763983, 2021). "Indications of pralsetinib for RET mutant MTC and RET fusion-positive thyroid cancer are under review." (PMID 33419162, 2021). "Selpercatinib and pralsetinib are a kinase inhibitor that blocks a type of enzyme (kinase) and prevents the proliferation of RET-altered non-small cell lung cancer (NSCLC) and certain types of thyroid cancer, including MTC." (PMID 34207842, 2021). "S897 phosphorylation of EphA2 has also been involved in determining the aggressiveness of thyroid cancer cells and shown to be mediated by ERK1/2 activation downstream of oncogenes like RET (RET/PTC), KRAS (G12R), or BRAFV600E." (PMID 33572284, 2021). "Oncogenic alteration of RET has been reported in both PTC and MTC; thus, the RET protein has become a promising target for thyroid carcinoma therapies." (PMID 33419162, 2021). "In the molecular diagnosis of thyroid cancer, the related molecular markers include TERT, BRAF, PAX8/ PPARγ, RAS and RET/PTC26." (PMID 31949496, 2020). "Taking BLU-667 as an example, it was reported to have 88-fold more potency against RET than VEGFR, and it has already demonstrated clinical benefits in RET-altered thyroid cancer and lung cancer patients in early stage clinical trials." (PMID 32293499, 2020). "Selpercatinib (LOXO-292) is the first approved RET-TKI with applications for advanced RET fusion-positive NSCLC, thyroid cancer, and RET-mutant MTC." (PMID 33109256, 2020). "RET/PTC3 (Ret proto-oncogene and Ret-activating protein ELE1) rearrangement is the most frequent genetic alteration in thyroid cancer and most functions of RET are mediated through pathways including ERK, JNK, and PI3K/AKT." (PMID 32752094, 2020). "Kinase fusions have been identified in distinct histological subtypes of thyroid cancer, including papillary thyroid cancer (PTC; RET, NTRK1/2/3), medullary thyroid cancer (ALK), and poorly differentiated thyroid cancer (RET, ALK)." (PMID 32292131, 2020). "Six molecular targets of thyroid cancer including BRAF, RET, NTRK1, G-GAS, K-RAS, and N-RAS have already been reported." (PMID 33519470, 2020).
thyroid cancer (continued). "MicroRNAs (miRNAs) have been shown to influence the activity of thyroid cancer-related signaling pathways such as MAPK pathway and RET gene." (PMID 32637757, 2020). "In a further study of nearly 33,000 cases of circulating free tumor DNA (cfDNA) from metastatic patients, RET fusion events were identified in NSCLC and in colorectal, breast, and thyroid carcinomas." (PMID 32326537, 2020). "These include CHEK2 mutations in breast cancers and also in a variety of other cancers including thyroid cancer, EWSR1 in Ewing sarcoma, RET in hereditary medullary thyroid carcinoma, NRP1 in breast cancer and germline POT1 variants in malignant melanoma." (PMID 31614935, 2019). "The induction of RET/PTC1 and BRAF p.V600E in thyrocytes and thyroid cancer cells resulted in the activation of NF-kB." (PMID 31835496, 2019). "Analyzed RET/PTC1 and RET/PTC3 are intrachromosomal inversions involving the RET and CCDC6 or NCOA4 genes, respectively, which are prevalent in thyroid cancers in individuals exposed to radiation after the Chernobyl nuclear accident." (PMID 29568381, 2018). "Epidermal growth factor receptor (EGFR)-dependent RET activation: an interaction between EGFR and RET was recently described, with EGFR reported to be over-expressed in thyroid cancer cells." (PMID 29057215, 2017). "However, Croyle found that these interactions were independent of the c-terminal moiety of RET which is inconsistent with our data and could be due to the different EGFR binding organization between RET fusion proteins in thyroid cancers and wild type RET in A+AD." (PMID 28460442, 2017). "As is well known, PTC, the most common thyroid carcinoma, frequently carries BRAF and RET/PTC, which have been identified as highly specific markers of thyroid cancer." (PMID 27654865, 2016). "RET, BRAF and other protein kinases have been identified as major molecular players in thyroid cancer." (PMID 27058903, 2016). "It has been also shown that CLM3 and CLM29 (another pyrazolo[3,4-d]pyrimidine, inhibiting RET, EGFR, and VEGFR, with antiangiogenic activity) inhibited the migration of papillary dedifferentiated thyroid cancer (DePTC) cells." (PMID 26635725, 2015). "Other rearrangements common to thyroid cancers include RET/PTC1 and RET/PTC3, which both result from intrachromosomal paracentric inversions and have a strong correlation with radiation exposure." (PMID 25276134, 2014). "Of note similar to RET, rearrangement of NTRK1 has been described in thyroid cancer (TPM3-NTRK1, TPR-NTRK1, TFG-NTRK1)." (PMID 24744988, 2014). "We compared the effect of SPP86 on MAPK kinase signaling and proliferation in RET/PTC1 (TPC1), BRAFV600E (8505C) and RASG13R (C643) expressing thyroid cancer cell lines." (PMID 25409876, 2014). "RET/PTC has been found to transform thyroid cells in culture and gives rise to thyroid carcinomas in transgenic mice." (PMID 23455356, 2013). "We investigated the effects of AZD1480 on IL-6/JAK and RET- dependent signaling (STAT3, ERK/MAPK and PI3K/AKT) as well as its biological effects in human thyroid cancer models (cell lines and a xenograft model)." (PMID 23056499, 2012). "RET/PTC exhibits transforming ability via effecting differentiation, mitogenic and metastatic potential in thyroid cancer." (PMID 22928011, 2012). "These biomarkers, such as CK19, TG, Ki67, Calcitonin, TTF-1, BRAF, RET, HBME-1, and galectin-3, have been translated into clinical practice which offered significant improvement in the preoperative diagnosis of thyroid cancer." (PMID 22188859, 2011).
thyroid cancer (continued). "Some proteins' alteration was found in thyroid cancer, such as CK19, TG, Ki67, Calcitonin, TTF-1, BRAF, RET, HBME-1, SERPINA1, TfR1/CD71, FHL1 and galectin-3." (PMID 22188859, 2011). "New types of RET/PTC have been identified in post-Chernobyl thyroid carcinomas that are generated by translocations instead of inversions like RET/PTC1 and RET/PTC3." (PMID 16641909, 2006). "Unlike thyroid cancer, where RET mutations predominate, NSCLC is mainly driven by RET fusions, most commonly with KIF5B (70–90%) and CCDC6 (10–25%) partners." (PMID 41228269, 2025). "RET and ALK fusions or high microsatellite instability are potential targets in thyroid cancer." (PMID 40844731, 2025). "Pralsetinib is another approved RET TKI for RET fusion‐positive NSCLC and thyroid cancer." (PMID 39950716, 2025). "The ‘liver neoplasms’ CTD over-representation could be attributed to cell cycle-related pathway enrichment and corresponding genes (cell cycle: PDS5A, ORC6, RAD21, ZBTB17; Thyroid cancer: CTNNB1, RET) identified from our CRIPSR screens." (PMID 41446233, 2025). "The ARROW trial enrolled 29 patients with RET+ solid tumors other than NSCLC and thyroid cancer." (PMID 39950716, 2025). "RET fusion and NTRK fusion are the most common rearrangements observed in thyroid cancer." (PMID 40586006, 2025). "According to the findings of phase 1/2 studies, two selective RET inhibitors, selpercatinib and pralsetinib, received accelerated FDA approval in 2020 for patients with RET fusion-positive non-small cell lung cancer (NSCLC) and thyroid cancer only." (PMID 41373459, 2025). "Thirty percent of thyroid cancers will not carry any of the known mutations involved in thyroid cancer initiation and progression (RAS, RET/PTC, or BRAF (V600E) mutations)." (PMID 39218967, 2024). "After eligibility criteria were applied, a total of 68 patients with RET fusion-positive a/m NSCLC who initiated selpercatinib were obtained from the FHD, while 75 patients, including those having lung (57.3%, n = 43) or thyroid cancer (32.0%, n = 24), were identified from CDM." (PMID 39594790, 2024). "Mutations in BRAF, RET/PTC, NTRK1, or RAS have been reported in up to 70% of differentiated thyroid cancers and historically it does not depend on an MMR deficiency." (PMID 39062638, 2024). "This trial evaluated 41 patients with RET fusion-positive tumors beyond NSCLC and thyroid cancer." (PMID 39518080, 2024). "The thyroid cancer cohort included both RET-mutant MTC and RET-rearranged thyroid cancer." (PMID 37627175, 2023). "Until the recently published data from LIBRETTO-431 and LIBRETTO-531, there were limited effectiveness data comparing selpercatinib with other first-line treatments in RET-activated non-small cell lung cancer (NSCLC), medullary thyroid cancer (MTC), and thyroid cancer (TC)." (PMID 38201566, 2023). "Selpercatinib received an accelerated approval from the FDA in May 2020 for treatment of patients with metastatic RET-fusion positive NSCLC, advanced/metastatic RET-mutant medullary thyroid cancer, and advanced/metastatic RET-fusion-positive thyroid cancer." (PMID 38118420, 2023). "For the tumor agnostic accelerated approval, efficacy was shown in 41 patients with RET fusion–positive tumors (other than NSCLC and thyroid cancer) with disease progression on or following prior systemic treatment or who had no satisfactory alternative treatment options." (PMID 38201460, 2023). "Next, we examined the efficacy of vepafestinib in blocking growth of 12 tumor cell lines (patient -derived and isogenic) that are models of RET fusions or RET mutations found in NSCLC and thyroid cancers and three nontumor cell lines." (PMID 37743366, 2023). "Similarly, pralsetinib accelerated approval for RET fusion-positive NSCLC came in September 2020 and in December 2020 for thyroid cancer based on the ARROW trial." (PMID 36690680, 2023).
thyroid cancer (continued). "Despite achievement in CCDC6-RET-rearranged thyroid cancer cells, they found that exposure to either cabozantinib (a non-selective RET-TKIs) or BLU6864 (a selective RET-TKIs) is associated with rapid inhibition of ERK1/2 signaling." (PMID 36768754, 2023). "Consequently, the FDA has approved it for patients with RET-mutant MTC and RET-positive thyroid carcinoma." (PMID 37345200, 2023). "After recent approvals of pralsetinib in patients with RET-altered NSCLC and thyroid cancers and respective publications of these data, here we present interim data on the efficacy and safety of pralsetinib in prospectively identified patients with diverse RET fusion–positive tumors." (PMID 35962206, 2022). "In The Cancer Genome Atlas (TCGA) study, NTRK fusions and RET fusions were found in 1.2 and 6.8% of mostly non-metastatic thyroid cancers." (PMID 34981751, 2022). "In this study, radiological progression of the disease according to RECIST within 14 months from the screening visit was an inclusion criteria for RET-mutant MTC patients but not for RET-fusion positive thyroid cancer." (PMID 35422765, 2022). "Although not the focus of this report, it is important to note that rare (<1%) hypersensitivity reactions to selpercatinib treatment have been observed in patients with RET-altered thyroid cancers, revealing these events are not specific to NSCLC." (PMID 35183775, 2022). "Studies have shown that the functional defect of DNA mismatch repair is most common in high mutation load thyroid cancer (46%), especially in ATC, and there is a lack of typical BRAF, RAS or RET thyroid oncogene mutations." (PMID 35865459, 2022). "Twenty-nine patients with 12 different RET fusion–positive solid tumor types, excluding non-small-cell lung cancer and thyroid cancer, who had previously received or were not candidates for standard therapies, were enrolled." (PMID 35962206, 2022). "This approach may be particularly suitable for patients with a high frequency of RET and TERT alterations, such as those with thyroid cancer." (PMID 36142729, 2022). "In 2020, RET‐selective inhibitors pralsetinib and selpercatinib received clinical approval for RET fusion‐positive NSCLC, RET‐mutant MTC, and RET fusion‐positive thyroid cancer based on the results of the phase I/II ARROW study and the phase I/II LIBRETTO‐001 trial, respectively." (PMID 36254250, 2022). "In combination with the robust activity seen in patients with NSCLC and thyroid cancer in the ARROW study, these data further support the potential of pralsetinib to address the unmet medical need across a broad range of RET-altered tumor types with differing histology." (PMID 35962206, 2022). "Lenvatinib is a TKI inhibiting VEGFR-1, 2, and 3, fibroblast growth factor receptor (FGFR)-1–4, platelet-derived growth factor receptor (PDGFR), RET and KIT signalling pathways, that has been approved for the treatment of differentiated thyroid cancer, but only scanty data exist on its use in MTC." (PMID 35521769, 2022). "Despite the morphological similarities, no immunohistochemical markers in common with thyroid carcinoma or RET/PTC alterations were detected." (PMID 34458945, 2022). "The two most common types of thyroid carcinoma, papillary and follicular carcinoma, harbor four non-overlapping genetic alterations—BRAF and RAS point mutations and RET/PTC and PAX8/PPARγ rearrangements in more than 70% of cases." (PMID 35634500, 2022). "RET fusion genes, another hallmarker in BRAF-like thyroid cancer, were detected in three Bethesda V/VI nodules, and all of these nodules were diagnosed as thyroid cancer after surgery." (PMID 34322384, 2021). "Retevmo (selpercatinib) was approved in May 2020 for the treatment of RET fusion-positive NSCLC, RET-mutant medullary thyroid cancer (MTC), and RET fusion-positive thyroid cancer." (PMID 33670524, 2021).